IL10 (interleukin 10)
Diseases named in the same sentence as IL10 in open-access papers (continued):
Sharing a sentence is not in itself a finding about the gene and the disease.
bladder cancer (continued). "Therefore, we propose evaluation of the effectiveness on tumor reduction of rBCG-S1PT, compared to BCG and PBS; and evaluation of the immune response profile focusing on TNF-α (Th1) and IL-10 (Th2) in an orthotopic bladder cancer animal model." (PMID 19040745, 2008). "Indeed, IL-10 deletion studies performed either by antibody inhibition or using gene knockout animals resulted in enhanced DTH response and antitumour activity, while IL-10 knockout mice also showed prolonged survival and response in a syngeneic model of orthotopic bladder cancer." (PMID 14676812, 2003). "As typical for human bladder cancers, the mouse MB49 tumor microenvironment is dominated by Th2 cytokines, such as IL-10, which leads to the accumulation of tolerogenic macrophages as well as regulatory T cells." (PMID 38259453, 2023). "Tumor-derived IL-10 induces dendritic cell (DC) dysfunction, resulting in impaired T-cell proliferation and IFN- production in murine bladder cancer." (PMID 37151396, 2023). "The levels of IL-6, IL-10, CCL2 were significantly decreased in both two bladder cancer cell lines, and Other transcription factors are uncertain in cell lines." (PMID 35769470, 2022). "Some of these genes were closely related to the occurrence and development of bladder cancer: CDK6, IL-10, and RUNX1, of which CDK4/6 inhibitors are a promising treatment strategy for the treatment of bladder cancer." (PMID 32655621, 2020). "In the murine bladder cancer model, treatment with rBCG-S1PT induced an increase in IL-10 mRNA and in the survival time of the animals." (PMID 31297119, 2019). "In fact, blocking IL-10 and TGFβ has been shown to reduce the induction of CD25+ve regulatory T cells in vitro by a bladder cancer cell line." (PMID 31824850, 2019). "An increased frequency of intratumoral FOXP3+ Tregs and inhibitory cytokines such as IL-10 and TGF-β was noted in bladder cancer patients compared to the healthy population." (PMID 27221038, 2016). "We thus proposed the evaluation and comparison of the immune balance responses of TNF-α and IL-10 to rBCG-S1PT and BCG in an animal model of orthotopic bladder cancer." (PMID 19040745, 2008). "Based on the fact that modulation of cytokines is important in cancer therapy, especially in the metaphylaxis of early stage bladder cancer, we investigated the effect of OR10H1 activation on the synthesis of cytokines, which revealed a significant increase in IL10 and IL15 upon stimulation." (PMID 29867524, 2018). "The finding that CpG-oligonucleotides can induce IL-12 production in DCs without concurrent production of IL-10 supports our hypothesis that DCs can be polarised to a Th1 immune response and that this can be manipulated to improve the efficiency of bladder cancer immunotherapy." (PMID 14676812, 2003). "Unlike other cytokines previously discussed, interleukin-10 (IL-10) is distinct in that its primary effect is to promote a Th2 response and thus dampen the immunotherapeutic effects of BCG for the treatment of bladder cancer." (PMID 22778725, 2012).
candidiasis (29 papers, 2007 to 2026). Infection with the organism Candida. "The autosomal dominant form is most commonly associated with pathogenic variants in STAT3 that impair Th17/IL-1, predisposing to Staphylococcus aureus and Candida infections, with dysregulated IL-6/IL-10 contributing to eczema-like lesions." (PMID 41378312, 2026). "A previous study has shown that administration of IL-10 increased host susceptibility to candidiasis, while IL-17, IFN-γ, IL-12, and IL-22 played an important role in protecting against candida." (PMID 32460890, 2020). "Susceptibility to candidiasis in mice was previously associated with activation of the Th2 subset and IL-10 production." (PMID 26010544, 2015). "Limited data from human studies have identified polymorphisms in the IL-10 gene associated with increased susceptibility to invasive candidiasis, whereas polymorphisms in the IL-10 promoter have been associated with either resistance or susceptibility to invasive pulmonary aspergillosis." (PMID 27973396, 2016). "Given these complexities, the functional impact of mXJ104-induced IL-10 in invasive candidiasis warrants further investigation." (PMID 40953078, 2025). "The inhibition of IL-4 signaling, and IL-10 knockout mice have been shown to enhance resistance to candidiasis." (PMID 39062060, 2024). "In response to an increase in IL-10, candidiasis prevalence increased by about 40% (OR = 1.40) and (P. value ˂ 0 / 001) in diabetic patients." (PMID 36443718, 2022). "This study aimed to investigate the association between IL-10 and IFN-γ serum levels in patients with oral Candidiasis and T2DM." (PMID 36443718, 2022). "Levels of interleukin IL-4, IL-8, IL-10 were quantified after Candida infection of PNT1A cells and treatment." (PMID 36555687, 2022). "Dectin-2 is also a pharmaceutical target to manipulate IL-10 production in vivo, and to treat chronic and refractory candidiasis." (PMID 33727664, 2021). "A previous study showed that Il-10 KO mice have a reduced kidney fungal burden, suggesting that IL-10 facilitates systemic candidiasis." (PMID 31474988, 2019). "C. albicans infection is associated with increased levels of pro inflammatory monocyte derived cytokines such as TNFα, IL-1, and IL-6 as well as high IL-10, which contribute to the suppression of immunity against candidiasis." (PMID 23144764, 2012). "In contrast to the role of IL-10 in mice, where deletion of IL-10 is protective against systemic candidiasis, we observed a protective effect of addition of IL-10 to chicken embryos at a susceptible age." (PMID 21603634, 2011). "Given the detrimental role of IL-4 and IL-10 in murine candidiasis, inhibition of cytokines of Th2-type function during infection could be beneficial." (PMID 35958550, 2022). "Interestingly, the protective or detrimental effects of IL-10 depended upon the degree of inflammation in an experimental candidiasis model." (PMID 34575795, 2021). "Considering of β-glucans exposed on the outer surface of the cell wall and circulating β-glucans in patients with invasive candidiasis, β-glucans of C. krusei may be one factor that promoted IL-10 production in T cells in murine systemic C. krusei infection." (PMID 33552998, 2020). "In candidiasis, increases in IL-10 and decreases in IFN-γ have been reported." (PMID 22550593, 2012). "Bozza and colleagues reported that CD4+CD25+ regulatory T cells in candidiasis are strictly dependent on the expression of B7 costimulatory molecules by IL-10-producing DCs, and are involved in the IFNγ/IDO-dependent pathway that controls the local inflammatory pathology." (PMID 18221522, 2008). "Furthermore, in a mouse model of systemic candidiasis (SC), equol treatment significantly decreased the fungal burden (liver, kidneys, and lung) in mice and local tissue damage, while enhancing the production of interleukin-10 (IL-10)." (PMID 39267283, 2024). "Disseminated candidiasis significantly increased IFNγ, WBC, and AL counts but affected IL10 insignificantly." (PMID 36477491, 2022).
candidiasis (continued). "Due to the dichotomous response variable (candidiasis positive or negative), multivariable logistic regression was used to determine the relationship between IL-10, IFN-γ and the development of candidiasis by controlling the HbA1c." (PMID 36443718, 2022). "Of the cytokines induced, IL-1α, IL-1β, IL-6, IL-10, IL-17A, IL-18, IFN-γ, and TNF-α have been previously shown to play an important role in the pathogenesis of invasive candidiasis in vivo." (PMID 22916017, 2012). "In the case of Candida infection, TLR2 induced proliferation and survival of regulatory T cells, which appeared largely responsible for the increased IL10 release induced by TLR2." (PMID 17676990, 2007). "Furthermore, EVs administered to mice before inducing candidiasis influenced higher levels of TNF-α, IL-4, IL-10, IL-12p70, TGF-β and IFN-γ." (PMID 39877654, 2024). "The mean IL-10 level in positive candidiasis samples was significantly higher than that in negative samples in both diabetic and non-diabetic groups." (PMID 36443718, 2022). "IL-10 levels were significantly higher in the non-diabetic group compared to the diabetic group in samples negative for candidiasis." (PMID 36443718, 2022). "Additionally, mice lacking Il-10 are resistant to acute systemic candidiasis, as manifested by a lower fungal burden in kidneys." (PMID 31474988, 2019).
chronic hepatitis C (29 papers, 2010 to 2025). "IL-10 production is also increased in monoinfected patients with chronic hepatitis C, the HCV RNA load is closely associated with IL-10 expressions, and inhibition of HCV replication was accompanied by a reduction in IL-10." (PMID 33435966, 2021). "This study evaluated the TNFA -308G>A and IL10 -1082A>G polymorphisms in the susceptibility and progress of chronic hepatitis C." (PMID 34732154, 2021). "Additional studies are required to define the roles of these factors in connection with IL10 polymorphisms in chronic hepatitis C." (PMID 24398031, 2014). "Taken together, the some investigation has shown that responsiveness to IFN-αtreatment in patients with chronic hepatitis C is closely linked to ATA haplotype of the IL-10 gene promoter." (PMID 21251301, 2011). "Moreover, in patients with chronic C hepatitis, circulating IL-10 levels were associated with sustained necroinflammation activity, suggesting a relationship between IL-10 and liver histology severity." (PMID 37894792, 2023). "Other studies have emphasized the protective role of IL-10 during the treatment of chronic hepatitis C infection: it reduced the severity of fibrosis in participants." (PMID 33125400, 2020). "There is evidence that a high percentage of circulating T reg cells in patients with chronic hepatitis C secretes IL-10 and TGF-β, when compared to the group that eliminated the virus spontaneously and the HD group." (PMID 31780860, 2019). "In another study, chronic hepatitis C patients presented elevated serum levels of IL-10, IFN-γ, IL-6, and IL-4, while IL-1, IL-2, IL17, IL-22, IL-13 TNF, IL-12p70, and IL-15 levels were lower in patients compared to healthy controls." (PMID 29977152, 2018). "In contrast, the levels of IFN-γ were described to be lower in another population of chronic hepatitis C patients compared to controls, while IL-4 and IL-10 were higher." (PMID 29977152, 2018). "Other studies have emphasized the protective role of IL-10 used in the treatment of chronic hepatitis c infection, which had decreased severity of fibrosis in enrolled individuals." (PMID 26742960, 2016). "In this study, the AA genotype for IL-10 (−1082) was more frequently observed in patients with chronic hepatitis C when compared to those that resolved infection spontaneously." (PMID 22986179, 2012). "Heterogeneity in the promoter region of the IL-10 gene has been reported to have a role in determining the initial and sustained response of chronic hepatitis C to IFN-αtherapy." (PMID 21251301, 2011). "Altogether, our observations raise the idea that reducing IL-10 and/or TGFβ bioavailability could be a suitable means to restore NK cell functions in chronic hepatitis C. However such approach could dangerously modify the overall equilibrium between effector and regulatory mechanisms." (PMID 21085608, 2010). "The elevated levels of IL-10 in the plasma of chronic hepatitis C (CHC) patients and their high degree of IL-10 reliance, both spontaneously and following HCV antigen stimulation, highlight its potential as a therapeutic target." (PMID 39459945, 2024). "A study from 2013 reported an inverse correlation between IL-10 levels and fibrosis stages in patients with CHC, while another showed that treatments with an IL-10 agonist reveal a decrease in fibrosis progression in chronic hepatitis C virus infection." (PMID 36674897, 2023). "In patients with chronic hepatitis C virus infection, M-MDSCs have higher levels of phosphorylated STAT3 and IL-10, while blocking STAT3 signaling reduces hepatitis C virus (HCV)-mediated M-MDSC expansion and IL-10 expression." (PMID 32793192, 2020). "On the other hand, it has been seen that patients with chronic hepatitis C treated with PEGIFN+RBV and presenting an increase in IL-10 regulatory cytokine may actually compromise the host immune response." (PMID 31780860, 2019). "Furthermore, IL-10+ CD8+ T cells have been found in patients with HIV and chronic hepatitis C infection." (PMID 28261215, 2017).
delirium (29 papers, 2011 to 2025). A disorder characterized by confusion; inattentiveness; disorientation; illusions; hallucinations; agitation; and in some instances autonomic nervous system overactivity. "IL-8 levels in the blood were associated with delirium in patients with infection, whereas IL-10 and amyloid-β 1–42 and 1–40 blood concentrations were elevated in delirium in non-infected patients." (PMID 37744876, 2023). "We previously found that delirium was associated with IL-8 (odds ratio, 9.0; 95% confidence interval, 1.8 to 44.0) and IL-10 (odds ratio, 2.6; 95% confidence interval, 1.1 to 5.9) but not with TNFα in inflamed ICU patients." (PMID 25042374, 2014). "Biomarkers that were significantly associated with delirium were IL-8, IL-1ra, IL-10, ratio Aβ1-42/40, and ratio AβN-42/40." (PMID 22206727, 2011). "Extended with the biomarkers TNF-α, IL-6, IL-18, IL-1ra, and IL-10, the 10 best biomarkers associated with delirium (all P < 0.10) were then entered into a multivariate logistic regression analysis." (PMID 22206727, 2011). "Among the pro-inflammatory cytokines, TNFα is upstream of 17 of the 32 CSF delirium-associated proteins, IFNγ has a potential connection to 15/32 CSF proteins, IL-6 is upstream of 10/32 proteins, and IL-10 is upstream of 8/32 proteins." (PMID 37759795, 2023). "In conclusion, among critically ill patients with delirium, our hypothesis-generating study suggests levels of IL-6 and IL-10 at one week of ICU stay may be associated with mortality." (PMID 37656731, 2023). "• Delirium in inflamed patients is independently associated with the proinflammatory cytokine IL-8, and in noninflamed patients, delirium is independently associated with the antiinflammatory cytokine IL-10 and the ratio amyloidβ-42/40." (PMID 22206727, 2011). "IL-6, IL-8, IL-10, IL-18, TNF-α, and chemokines (CCL2, CCL3, CXCL1, and CXCL10) have also been reported to be elevated in ICU delirium patients and are associated with delirium severity." (PMID 39308447, 2024). "Among the unique proteins, we focused on the top 13 most investigated proteins (IL-6, CRP, IL-8, S100B, IL-10, TNF-a, IL-1b, Cortisol, MCP-1, GFAP, IGF-1, IL-1ra, and NFL) that are significantly associated with delirium." (PMID 39700095, 2024). "Inflammatory mediators such as IL-1B, IL-6, IL-8, IL-10, TNF-alpha, and C-reactive protein (CRP), have all shown associations with delirium." (PMID 36803215, 2023). "The additional measurement of interleukin (IL)-6, IL-8, IL-10 and tumor necrosis factor-α increases the accuracy to predict delirium and an unfavorable outcome." (PMID 37744876, 2023). "It has also been shown that decreasing the expression of IL-6 and upregulating the expression of IL-10 in the peripheral blood, hippocampus, and prefrontal cortex reduces microglia activation and reduces delirium-like behavior in mice." (PMID 37025488, 2023). "A recent systematic review has shown that IL-1β, IL-6, IL-8, IL-10, and IFN-γ are significantly associated with delirium onset, displaying higher levels, both in plasma and CSF, in relation to baseline." (PMID 34736422, 2021). "In the same study, they also found higher levels of neopterin and IL-10 in hypoactive patients than in the mixed-type delirium group." (PMID 32987655, 2020). "We found levels of neopterin and IL-10 before the onset of delirium to be significantly higher in patients with hypoactive delirium compared to patients with mixed-type delirium." (PMID 29801516, 2018). "Levels of neopterin and IL-10 were significantly higher compared to levels in patients with mixed-type delirium." (PMID 29801516, 2018). "Levels of neopterin and IL-10 were significantly higher in hypoactive delirium compared to mixed-type delirium." (PMID 29801516, 2018). "Ritter and colleagues studied TNFα, soluble TNF receptor (STNFR)-1, STNFR2, IL-1β, IL-6, IL-10 and adiponectin in systemic inflamed patients in relation to delirium." (PMID 25042374, 2014).